LIFR (LIF receptor subunit alpha)
Diseases named in the same sentence as LIFR in open-access papers (continued):
Sharing a sentence is not in itself a finding about the gene and the disease.
tumor (continued). "LIFR expression (detected in 16 of 24 patients all of whom received neoCRT) was significantly reduced in tumour biopsies from patients having a subsequent poor pathological response to neoCRT (p<0.001), when compared to good responders." (PMID 30263091, 2018). "Outside this grouping, a cartilaginous fish sequence falls within an OSMR (multifunctional) and LIFR (tumour metastasis suppressor) clade (BPP = 1.00; UB = 1.00%; PPP = 1.00)." (PMID 30442091, 2018). "LIFR mRNA expression was significantly reduced in treatment naïve OAC tumour biopsies from patients having a subsequent poor pathological response to treatment, suggesting that a loss in receptor expression is associated with poor treatment response." (PMID 30263091, 2018). "Unpublished NGS data from nearly 60 NPC patient tumor samples also revealed genetic alterations of LIFR in NPC tumors." (PMID 30504771, 2018). "Taken together, these findings suggest LIFR as prognostic marker for tumor progression, combination of LIFR and relevant genes are more efficient to evaluate prognoses." (PMID 30012200, 2018). "IL10 and the gene encoding its receptor IL10R were expressed mainly by TAMs, LIF and LIFR by tumor cells, IL6 and the genes for IL6 receptor subunits IL6R and IL6ST by both cell types." (PMID 27215396, 2016). "Notably, CAF-FAP and CAF-C7 both showed upregulated chemokine signaling pathway, but showed high expression of pro-inflammatory genes (CCL2, CXCL12, GDF15, and LIFR) at tumor core and pro-fibrotic genes (TNFRSF12A, TGFBR1, TGFBR2) at FR, respectively." (PMID 39870619, 2025). "This down-regulation of LIFR may contribute to the progression of cancer cells out of dormancy, increasing their aggressiveness and proliferation, and thereby promoting tumor growth." (PMID 40977686, 2025). "Furthermore, miR‐589–transfected cells treated with LIFR exhibited a two‐fold reduction in cellular invasion, supporting the role of LIFR as a potential tumor suppressor." (PMID 41163398, 2025). "While EC359 alone did not impair basal proliferation, it attenuated LIF‐driven oncogenic activity, suggesting that LIFR blockade may be a viable strategy to counteract LIF‐mediated tumor progression in GC." (PMID 41163398, 2025). "Furthermore, we presented proof that inhibiting LIFR signaling lowers stemness and increases anti-tumor immunity." (PMID 38789520, 2024). "LIF treatment could thus represent a targeted anti-CSC strategy to fight against metastatic GC, and LIFR detection in primary tumours could constitute a potential new prognosis marker in this disease." (PMID 38453889, 2024). "Collectively, LIFR served as an anti-tumor gene in multiple human cancers." (PMID 36925915, 2023). "The results suggested that “JAK-STAT signaling pathway”, “signaling pathways regulating pluripotency of stem cells” and “Wnt signaling pathway” might be related to the tumor pathogenesis function of LIFR." (PMID 36925915, 2023). "Next, we analyzed LIFR expression across 33 tumor types in TCGA via the TIMER database." (PMID 36925915, 2023). "Our results revealed the function of LIFR as a tumor suppressor in multiple tumors, indicating the low levels of LIFR expression may decrease patient survival rates." (PMID 36925915, 2023). "In HCC tumor tissues, LIFR was significantly reduced by increased hypermethylation of its promoter." (PMID 36062165, 2022). "Furthermore, LIFR expression restoration in malignant tumor cells triggered the Hippo signaling that led to functional inactivation of oncogenic YAP." (PMID 35163731, 2022). "Many studies proved LIFR could repress some tumor, and our study was the first to prove miR-21 could suppress the mRNA of LIFR to promote the tumor progression." (PMID 36062165, 2022). "Therefore, these suggest that LIFR as a biomarker of tumor progression is more effective in assessing prognosis." (PMID 36062165, 2022).
tumor (continued). "This is not to say that LIF and LIFRβ are not relevant; however, but rather that the focus of the conversation surrounding them in cancer should be shifted towards how LIF and LIFR can be understood through the lens of tumor suppression and promotion via the less understood Hippo pathway." (PMID 34395259, 2021). "Moreover, intracardiac injection of MCF7 LIFR knockdown cells into mice results in greater bone destruction via increased osteoclastogenesis and tumor cell proliferation." (PMID 33828987, 2021). "In vivo studies demonstrated that LIFR-KO significantly reduced EC xenograft tumor growth." (PMID 34400617, 2021). "Despite this, recent insights into their functional roles in cancer have highlighted interesting patterns that may allude to a broader understanding of LIF and LIFR within tumor growth and metastasis." (PMID 34395259, 2021). "We next determined whether the LIFR-KO could reduce tumor progression in vivo using a mice xenograft model." (PMID 34400617, 2021). "LIFR-KO significantly reduced EC xenograft tumor growth compared to vector controls." (PMID 34400617, 2021). "Several other ligands (OSM and CNTF included) are also able to bind to LIFR, which may mediate the tumor-suppressive actions of LIFR." (PMID 32023849, 2020). "This might be a reason for the finding that LIFR inhibition is a more efficient approach to prevent tumor formation than LIF inhibition." (PMID 32651426, 2020). "Our study put forward for the first time that cynaropicrin can inhibit the proliferation of CRC and induce its apoptosis by targeting the LIFR/STATs axis in vitro and in vivo, suggesting that cynaropicrin is a potential natural product with anti-tumor efficacy." (PMID 33505963, 2020). "It has been suggested that LIFR may be reduced in tumour tissues as a result of the promoter undergoing hypermethylation." (PMID 30263091, 2018). "Also, through the increased hypermethylation of its promoter, LIFR is observed to be markedly reduced in HCC tumor tissues." (PMID 30012200, 2018). "Moreover, we focused on several tumor suppressor genes; of these, LIFR was a promising candidate target gene of miR-629-3p after evaluation with qRT-PCR, Western blotting, and luciferase reporter assays." (PMID 28629464, 2017). "MiR-125a suppression could significantly control the CSC population and tumor suppression through LIFR, thus activating tumor suppression and the Hippo signaling pathway." (PMID 25962054, 2015). "Preliminary data suggest that high LIFR expression is associated with worse outcomes in advanced GC, while LIF expression may correlate with improved responsiveness to chemoimmunotherapy and favorable remodeling of the tumor immune microenvironment." (PMID 41163398, 2025). "Furthermore, we validated a tumor suppressor role of LIFR in UCEC." (PMID 36925915, 2023). "LIFR showed the highest expression in midbrain, followed by basal ganglia and thalamus, with low tissue specificity, while low expression of LIFR was detected in most tumor cell lines, with higher expression in AF22 (brain), SCLC-21H (lung) and HHSteC lines (mesenchymal)." (PMID 36925915, 2023). "However, current studies have limited the investigation of LIFR to a few tumor types, and the correlation with prognosis and immune parameters remains unclear in most cancers." (PMID 36925915, 2023). "LIFR expression was detected as a faint signal in gastric glands on the normal mucosa, but the signal increased dramatically in the cancer tissues, showing a strong localization on the cell membrane of cancer cells (arrow), whereas some scattered signals were also detected in the tumor matrix." (PMID 35847866, 2022). "In addition, we found that LIFR was a target gene regulated by miR-21, and LIFR also could promote the apoptosis of tumor cells." (PMID 36062165, 2022). "Therefore, targeting the miR‐3682‐3p‐LIFR axis or other target gene axis might impede tumor development in EC." (PMID 33463006, 2021).
tumor (continued). "Moreover, immunotherapy of LIFR was a more efficient approach in the inhibition of tumor growth." (PMID 32651426, 2020). "The cytokines capable of binding to LIFR and the other cytokine-specific receptors in the gp130 family are produced by bone-resident osteoblast and osteoclast-lineage cells and are therefore likely to reach bone-disseminated tumor cells and alter their behavior and signaling." (PMID 32023849, 2020). "LIFR was found to promote membrane localisation factor Scribble which in turn led to the activation of Hippo signalling and phosphorylation and functional inactivation of the transcriptional co-activator Yes-associated protein 1 (YAP1) and subsequent suppression of tumour metastasis." (PMID 30263091, 2018). "Bulk RNA‐seq and single‐cell RNA‐seq of 37 PC specimens revealed enrichment and positive correlation of SOX9, LIF, LIFR, and IL6ST (GP130) in tumor cells." (PMID 41163398, 2025). "Compared to other EC subtypes,EC4 exhibited elevated expression levels of multiple genes implicated in antigen presentation (HLADRB1,HLA-DRB5,and HLA-DRA),immune cell recruitment (SELP,LIFR, and ACKR1),and anti-tumor inflammation (CCL14,IFITM1)." (PMID 41394809, 2025). "In this study, LIFR, a leukemia inhibitory factor receptor, interacts with LIF to trigger multiple signaling pathways, including those promoting tumor progression and metastasis as well as inhibiting tumor proliferation and invasion." (PMID 40108662, 2025). "Previous studies indicate that HDAC inhibition promotes LIFR transcriptional activation, which in turn activates the JAK1-STAT3 pathway and the antiapoptotic cascade, a mechanism contributing to tumor resistance to HDAC inhibition." (PMID 40296045, 2025). "Using multiple preclinical models, we demonstrate that EC359 suppresses LIFR signaling, enhances the efficacy of the MEK inhibitor trametinib, and inhibits tumor growth both in vitro and in vivo." (PMID 41154625, 2025). "This study showed that miR‐589 directly suppresses LIFR expression, thereby enhancing PI3K/AKT/c‐Jun signaling and acting as a tumor‐promoting factor in GC tumor specimens." (PMID 41163398, 2025). "Leukemia inhibitory factor (LIF) and its receptor, leukemia inhibitory factor receptor (LIFR), have been identified as being overexpressed in GC tissues; their role in tumor differentiation, lymphovascular invasion, and metastasis is under investigation." (PMID 41163398, 2025). "In contrast to LIFR, OSMR is highly expressed in fibroblasts, endothelial cells, and predominantly expressed in tumor cells compared to normal epithelial cells." (PMID 38839865, 2024). "The link between SOX9, expressed in tumor cells, and the CSF-1R, expressed by TAMs and particularly by the M2-like subset, is mediated by LIF/LIFR signaling." (PMID 39457693, 2024). "SIRT2 reverses the GCN5-induced acetylation of LIFR at K620, disrupting its homodimerization, PDPK1 activation, and AKT signaling, thereby attenuating tumor growth and positioning LIFR-K620 acetylation as a biomarker and therapeutic target in PCa." (PMID 39796040, 2024). "Our findings utilizing various LIFR-KO and OCa models showed that LIF is produced by OCa cells and is crucial for OCa proliferation and tumor development via LIFR in an autocrine way." (PMID 38789520, 2024). "LIF/LIFR activation occurs more prominently in TNBC compared to estrogen receptor positive (ER+) BC, and high circulating LIF levels correlate with tumor recurrence and contribute to chemoresistance." (PMID 39518071, 2024). "LIFR (leukemia inhibitory factor receptor) and PRIM2 are known to promote tumor growth, metastasis, and angiogenesis and increase angiogenic activity and coronary artery disease." (PMID 39048584, 2024). "This pattern of increased LIFR expression with deletion of the PTHrP NLS and C-terminal domain (compared to NLS alone deletion) mirrored the previously observed trend in tumor p27 expression." (PMID 38409028, 2024).
tumor (continued). "In contrast, significantly increased methylation of LIFR DNA promotor was observed in COAD, LUAD and READ tumor tissues according to the UALCAN database." (PMID 36925915, 2023). "Vimentin plays an important role in tumor invasion and metastasis, and its counter-regulation is a further evidence of the role that LIF/LIFR signaling plays in the modulation of EMT process." (PMID 35847866, 2022). "Meanwhile, there are studies reported that LIFR activates the JAK/STAT, ERK/MAPK, and Akt/PI3K pathways in tumor formation, inflammation, and cardiac function." (PMID 35093095, 2022). "Inhibition of LIF signaling by genetic LIFR deletion, LIF knockdown, or treatment with LIF neutralizing monoclonal antibodies leads to a reduction in tumor progression in mouse PDAC models and decreases tumor engraftment and growth in PDAC xenograft models." (PMID 35565185, 2022). "Studies have reported that LIFR activates the JAK/STAT, ERK/MAPK, and Akt/PI3K pathways in tumor formation, inflammation, and cardiac function." (PMID 35093095, 2022). "AKT-mediated phosphorylation events involving leukemia inhibitory factor receptor (LIFR) and its downstream target, ERK2, activate a signaling cascade that promotes tumor growth and metastasis." (PMID 36551580, 2022). "Preclinical xenograft, patient-derived explant, and xenograft studies demonstrated that LIFR inhibitor, EC359 is potent in reducing EC tumor growth and the therapy is well tolerated in vivo." (PMID 34400617, 2021). "With the decrease in H3K4me1 level at enhancers, transcription factors such as LIFR and KLF4 were markedly downregulated, effectively inhibiting tumor progression." (PMID 34758724, 2021). "Taken together, these findings showed that low expression of LIFR signified higher immune cells and stromal cell infiltration in TME and lower tumor purity in EC." (PMID 33463006, 2021). "SH2 superbinder has been verified to block the LIFR/STAT3 pathway and interrupt the tumor progression." (PMID 33783993, 2021). "We found an inverse relationship between the rate of tumor formation and the defense responses induced by the injection of LIF and LIFR." (PMID 32651426, 2020). "LIFR injection, individually or in combination with LIF, strongly inhibited the tumor growth to only 25% of the mice." (PMID 32651426, 2020). "As expected, many DMGs that were hypermethylated and downregulated in CMT including TP63, LIFR, PLA2G16, LRIG1, STAT5A, and AKAP12 and have been known as tumor suppressors, were identified from high scoring (OncoScore > 50) CMT-DMRs." (PMID 32693820, 2020). "We used IHC methods to determine LIFR, PIK3R1, and MMP12 protein expression in 20 GBC tumor tissues and patient-matched adjacent peritumor tissues." (PMID 31119098, 2019). "In GC, LIFR is positively regulated by LncRNA-LOWEG, which is a tumor suppressor inhibiting cell invasion." (PMID 30012200, 2018). "We next determined the levels of protein expression for several examples by flow cytometry of non-separated ascites samples and confirmed the preferential expression of S100A8/A9 and IL-8 in TAMs, and of LIFR and TGFBR3 in tumor cells." (PMID 27215396, 2016). "Results show that LIF and LIFR expression were higher in neoplastic than in control cholangiocytes; LIF was also expressed by tumor stromal cells." (PMID 26296968, 2015). "Additionally, parathyroid hormone-related protein (PTHrP), synthesized by tumor cells, disrupts leukemia inhibitory factor receptor (LIFR) signaling, further facilitating tumor cell exit from dormancy and enhancing metastatic growth." (PMID 40444046, 2025). "In addition, the leukemia inhibitory factor receptor (LIFR) participates in signaling pathways that promote dormancy and transiently halt tumor progression." (PMID 40977686, 2025).
tumor (continued). "The effects of BAR502, a non‐bile steroidal ligand of the Farnesoid X Receptor (FXR) and G Protein–Coupled Bile Acid Receptor 1 (GPBAR1), have been investigated on tumor proliferation and epithelial‐mesenchymal transition (EMT), with a focus on selective LIFR antagonism." (PMID 41163398, 2025). "Moreover, we provided evidence that LIFR inhibitor EC359 inhibited the growth of OCa cells in vitro and tumor progression in cell-derived xenografts (CDX) and patient-derived xenograft (PDX) models." (PMID 38789520, 2024). "Currently, it remains unknown whether the autocrine LIF/LIFR loop, other tumor intrinsic, as well as external effects of the LIF/LIFR axis drive the progression of OCa." (PMID 38789520, 2024). "We then performed cell viability assays using 24 OCa cell lines representing four different subtypes of OCa including 12 established, six primary tumor derived and six ascites-derived OCa cell lines to see if addition of LIFR inhibitor EC359 blocks LIF/LIFR autocrine signaling." (PMID 38789520, 2024). "Moreover, CellChat analysis unveiled ligand-receptor pairs mediating communication between tumor epithelial cells and disulfidptosis-related TME subgroups, such as TNFSF12-TNFRSF12A, TNF-TNFRSF1A, OSM-(OSMR+IL6ST), OSM-(LIFR+IL6ST), HBEGF-EGFR, and EREG-EGFR." (PMID 38292868, 2024). "Since a high p38/ERK signaling ratio promotes tumor dormancy, we also analyzed phosphorylated p38 levels in the PTHrP mutant cells, with and without LIFR inhibition." (PMID 38409028, 2024). "We analysed the intercellular networks about LIF/LIFR and found that interactions occurred frequently between TM4SF1+ tumor cells and proliferative tumor cells, indicating that LIF were mainly secreted from TM4SF1+ or proliferative tumor cells exerted an effect on other cell types." (PMID 37360193, 2023). "Because data on normal tissue distribution was not available for some tumor types in TCGA, we next analyzed differential expression of LIFR between normal and tumor tissues via the GTEx database." (PMID 36925915, 2023). "Upon binding, LIFR phosphorylates downstream proteins in the JAK-STAT3 signalling cascade; the inhibition of LIFR signalling has shown beneficial effects on cell growth and tumour progression in several cancers." (PMID 36359879, 2022). "Moreover, with the decrease in H3K4me1 level at enhancers, transcription factors such as LIFR and KLF4 were markedly downregulated, effectively inhibiting tumor progression." (PMID 34758724, 2021). "It was determined that circCRIM1 could sponge miR-182 and miR-93 to upregulate leukemia inhibitory factor receptor (LIFR) expression, a well-known tumor suppressor." (PMID 33717646, 2021). "Immunostaining of the tumor sections confirmed the expression of LIF and LIFR." (PMID 32651426, 2020). "The candidate tumor suppressor genes were ZBTB16, MAL, LIFR, and SLIT2." (PMID 33193630, 2020). "The tumor suppressor genes were ZBTB16, MAL, LIFR, and SLIT2." (PMID 33193630, 2020). "Furthermore in NPC, treatment with soluble LIFR, an antagonist of LIF or rapamycin, an mTOR inhibitor of LIF, was found to reduce cell survival and tumour growth following irradiation in-vitro and in-vivo." (PMID 30263091, 2018). "Furthermore, it has been reported that LIFR is a tumor suppressor gene in HCC and its down-regulation in tumor tissues is mostly dependent on promoter hypermethylation." (PMID 25749520, 2015). "We did not observe any significant correlation between cytoplasmic LIFr staining and tumor location." (PMID 26329521, 2015). "Therefore, the de novo expression of LIF and the up-regulation of LIFR in CCA bile ducts, along with LIF overexpression in the tumor reactive stroma, indicate the presence of autocrine and paracrine LIF-mediated mechanisms in CCA." (PMID 26296968, 2015). "Another interesting finding was the over-expression of LIF in tumor, whose receptor LIFR was over-expressed in adjacent mucosa but not in the tumor." (PMID 24597571, 2014).